TMEM220 (transmembrane protein 220)
Tractability: Antibody: UniProt predicts a signal peptide or a membrane-spanning region.
Gene: Protein-coding gene on chromosome 17 (10,699,015 to 10,730,354, reverse strand). Ensembl gene ENSG00000187824.
Subcellular location: Membrane
Gene Ontology:
Molecular function: protein binding
Cellular component: membrane
Genetic constraint (gnomAD): Loss-of-function variants: 19 observed, 19.47 expected, observed/expected ratio (o/e) 0.98, 90% interval 0.68 to 1.43. The upper end of that interval is the gene's LOEUF score, 1.43, which puts it in group 5 of 6, group 1 being the genes least tolerant of losing a copy. Missense variants: 139 observed, 168.97 expected, observed/expected ratio (o/e) 0.82, 90% interval 0.72 to 0.95. Synonymous variants: 56 observed, 58.62 expected, observed/expected ratio (o/e) 0.96, 90% interval 0.77 to 1.19.
Homologues: Orthologues: chimpanzee TMEM220 (99% identical), macaque TMEM220 (92% identical), pig TMEM220 (79% identical), rat Tmem220 (79% identical), mouse Tmem220 (78% identical), dog TMEM220 (70% identical), guinea pig TMEM220 (62% identical), rabbit TMEM220 (54% identical), tropical clawed frog tmem220 (51% identical).
Diseases named in the same sentence as TMEM220 in open-access papers:
TMEM220 is named in the same sentence as 11 diseases in open-access papers, as found by Europe PMC text mining. Sharing a sentence is not in itself a finding about the gene and the disease. The quoted sentences say what the papers report.
gastric cancer (3 papers, 2021 to 2025). A primary or metastatic malignant neoplasm involving the stomach. "Previous studies indicated that TMEM220 is hypermethylated in gastric cancer and colon adenocarcinoma." (PMID 40234942, 2025).
hepatocellular carcinoma (2 papers, 2025). A malignant tumor that arises from hepatocytes. "Other investigators reported that the expression level of TMEM220 is low in hepatocellular carcinoma and is associated with poor prognosis in patients, indicating that downregulation of TMEM220 promotes the progression of hepatocellular carcinoma." (PMID 40234942, 2025). "Limited coverage revealed that TMEM220 is downregulated in hepatocellular carcinoma, and several prognostic signatures contrasted by markers including TMEM220 displayed excellent prognostic prediction effect for hepatocellular carcinoma." (PMID 40557150, 2025).
breast carcinoma (1 paper, 2025). "There is a number of scientific research for each of the top 10 mRNA genes, well-documenting their significance and association with cancerogenesis: ADAMTS5, TMEM220, ARHGAP20, MICU3; or precisely with breast cancer: COL10A1, MMP11, CAVIN2 (formerly known as SDPR), PLPP3, MME, and CD300LG." (PMID 40724805, 2025). "The down-expression of TMEM220 and SHE genes (also in connection with hyper-methylation) has been repeatedly indicated as a significant factor important in the formation and development of cancer but not necessarily breast cancer (Refs." (PMID 40724805, 2025).
cancer (3 papers, 2021 to 2025). A tumor composed of atypical neoplastic, often pleomorphic cells that invade other tissues. "Thus, alterations in TMEM220 promoter methylation in UC may contribute to the similar pathway variations and promote cancer progression." (PMID 40234942, 2025). "Our analyses suggest that the three markers, VIM, TMEM220, and PPM1 N, exhibit significantly higher methylation levels in urinary tumor DNA (utDNA) relative to non-cancer specimens." (PMID 40234942, 2025). "An analysis of sensitivity for UC detection and specificity among other cancers, benign lesions, and non-neoplastic individuals was conducted for the three-marker combined model (PPM1 N, TMEM220, and VIM) as well as for each marker individually." (PMID 40234942, 2025).
tumor (3 papers, 2021 to 2025). "CBLN2 and TMEM220 protein expression levels were significantly different in tumor tissues as compared to controls." (PMID 34182539, 2021).
TMEM220 also shares sentences with these, for which no sentence is quoted: bladder cancer (1 paper); chronic myeloid leukemia (1); colon adenocarcinoma (1); colorectal cancer (1); head and neck cancer (1); prostate carcinoma (1).